U3 (Small nucleolar RNA U3 )
Synonyms: LOC124901860
Gene: Small nucleolar RNA gene on chromosome 7 (10,222,797 to 10,223,011, forward strand). Ensembl gene ENSG00000212422.
Gene Ontology:
Biological process: RNA processing
Cellular component: nucleolus
Homologues: Orthologues: chimpanzee U3 (98% identical), macaque U3 (88% identical), rabbit U3 (59% identical), rat LOC120102769 (59% identical). Paralogues in human: SNORD3P1 (80% identical), U3 (80% identical), U3 (78% identical), SNORD3G (77% identical), U3 (76% identical), SNORD3E (75% identical), U3 (75% identical), SNORD3D (74% identical), SNORD3H (74% identical), U3 (74% identical), U3 (73% identical), U3 (72% identical), and 11 more.